THRA (thyroid hormone receptor alpha)
Diseases named in the same sentence as THRA in open-access papers (continued):
Sharing a sentence is not in itself a finding about the gene and the disease.
anemia (3 papers, 2017 to 2021). A reduction in the number of red blood cells, the amount of hemoglobin, and/or the volume of packed red blood cells. "In the present study, we first characterized the erythroid phenotypes in Thra1PV/+ mice and showed that Thra1PV/+ mice exhibit anemia with decreased red blood cells and reduced hemoglobin content similar to patients with mutations of the THRA gene." (PMID 28910278, 2017). "Because patients with mutations of the THRA gene exhibit anemia, we focused our studies on the erythroid lineage." (PMID 29273766, 2017).
breast tumours (3 papers, 2013 to 2018). "This RNA was extracted from an additional n = 27 breast tumours, n = 20 fibroadenoma and n = 15 normal breast tissues was quantified by RQ-PCR targeting RARβ and THRα." (PMID 25934412, 2015).
gastric cancer (3 papers, 2021 to 2025). A primary or metastatic malignant neoplasm involving the stomach. "Indeed, some data have described mutations in the THRA gene in gastric cancers (essentially deletions), and mouse models have assigned oncogenic functions to mutated TRα1." (PMID 36217307, 2022). "Furthermore, only a few of the top twenty transcription factors identified are expressed among the gastric cancer cell lines and do not appear to be greatly affected by DCB treatment, including RARA, ATF1, THRA, and MEF2A." (PMID 41280003, 2025).
Insulin resistance (3 papers, 2013 to 2024). Increased resistance towards insulin, that is, diminished effectiveness of insulin in reducing blood glucose levels. "In conclusion, our work clearly underlines that deletion or mutation in THRa gene affecting p43 expression or function, could induce an increase glycemia, glucose intolerance and an insulin resistance several features of type-2 diabetes in patients." (PMID 24098680, 2013). "The disruption of the DIO2 gene and thyroid hormone receptors (THRα) gene, in contrast to the DIO3 gene, leads to a reduction in fat metabolism and an elevation in insulin resistance and visceral obesity." (PMID 38702594, 2024). "So that the disruption in DIO2 and thyroid hormone receptors (THRα) gene, unlike DIO3 gene, caused a decrease in fat metabolism along with an increase in insulin resistance and visceral obesity, which indicates the beneficial function of this deiodinase to prevent the development of obesity." (PMID 38702594, 2024).
Thyroid hormone resistance (3 papers, 2015 to 2024). "This is especially true due to the therapeutic options that are available, such as the treatment of patients with THRA mutations with L-thyroxine, and that will be developed in the near future for these thyroid hormone resistance diseases." (PMID 39201272, 2024). "Thyroid hormone resistance is caused by autosomal dominant inheritance of mutations in the thyroid hormone receptor (THR) genes THRα and THRß which encode intranuclear T3 receptors, resulting in T3 receptor dysfunction." (PMID 36004344, 2022). "Thyroid hormone resistance is most commonly found in THRB gene mutations and more rarely in THRA mutations; in some cases both genes are unchanged (non-TR RTH)." (PMID 25908941, 2015).
Anxiety (2 papers, 2022 to 2025). Intense feelings of nervousness, tension, or panic often arise in response to interpersonal stresses. "Research has demonstrated that thyroid hormone receptor alpha 1-knockout animals show higher levels of anxiety, while beta-knockout males display lower levels of anxiety." (PMID 40427032, 2025). "Moreover, our observations that Mct8ko mice display anxiety-related behavioral abnormalities, despite unaltered locomotor activity, are in agreement with prior studies on mice globally expressing a mutant form of the thyroid hormone receptor alpha 1 (TRa1) with a 10x lower affinity towards TH." (PMID 35159334, 2022).
atherosclerosis (2 papers, 2019 to 2020). A disease characterized by the build-up of fatty material and calcium deposition in the arterial wall resulting in partial or complete occlusion of the arterial lumen. "Further suggesting an anti-inflammatory effect of thyroid hormones, additional knockout of the thyroid hormone receptor alpha in apoE knockout mice, a commonly used atherosclerosis model, increased both atherosclerotic plaque size, and plaque inflammation." (PMID 30859432, 2019).
colorectal cancer (2 papers, 2022 to 2023). A primary or metastatic malignant neoplasm that affects the colon or rectum. "Interestingly, the relevance of these observations has been demonstrated in clinics, given that the THRA gene and the TRα1 isoform are frequently overexpressed in human colorectal cancer (CRC) patients." (PMID 36217307, 2022). "Importantly, THRA is upregulated in colorectal cancers, particularly in the high‐Wnt molecular subtype." (PMID 36217307, 2022). "Also, a study on 59 colorectal carcinomas reported a significant overexpression of THRα1 in advanced-stage cancers compared to early-stage cancers, similar to what we observed in ATC cells, that markedly upregulate THRα compared to nontumoral thyroid cells while inhibiting the THRβ transcription." (PMID 36877008, 2023).
Fibroadenoma (2 papers, 2011 to 2015). A benign tumor of the breast characterized by the presence of stromal and epithelial elements. "Total RNA extracted from malignant (n = 75), normal (n = 15), and fibroadenoma (n = 10) breast tissue biopsies was analysed using RQ-PCR targeting NIS, RARα, RARβ, ERα, PI3K, THRα and THRβ." (PMID 21283523, 2011). "Human breast tissue specimens (malignant n = 75, normal n = 15, fibroadenoma n = 10) were analysed by RQ-PCR targeting NIS, receptors for retinoic acid (RARα, RARβ), oestrogen (ERα), thyroid hormones (THRα, THRβ), and also phosphoinositide-3-kinase (PI3K)." (PMID 21283523, 2011).
Intellectual disability (2 papers, 2019 to 2024). "We report that mutations in the thyroid hormone receptor α1 gene (THRA) that result in intellectual disability also reduce brain size." (PMID 31628250, 2019). "Interestingly, a recent report described a patient with a specific genetic mutation in the THRα gene sequence, resulting in an increased THRα2 antagonism, which led to neuronal hypothyroidism and intellectual disability." (PMID 39515608, 2024).
ovarian carcinoma (2 papers, 2020 to 2023). A malignant neoplasm originating from the surface ovarian epithelium. "Depending on nuclear or cytoplasmic expression, our study shows that THRα and its isoforms 1 and 2 provide different prognostic information for ovarian cancer patients." (PMID 32533406, 2020). "Moreover, THRA (thyroid hormone receptor alpha) has been studied in thyroid, breast, and ovarian cancer." (PMID 36838660, 2023). "Because the exclusive expression of the FSHR has already been described by our group as a negative prognosticator in ovarian cancer cases, our finding about enhanced expression of both FSHR and THRα in the nucleus might lead to new treatment strategies for this type of cancer." (PMID 32533406, 2020).
abortion (1 paper, 2023). the ending of pregnancy by removing a fetus or embryo before it can survive outside the uterus. "The expression of thyroid hormone receptors (THRα and THRβ) in placenta villi and decidual tissues in spontaneous abortion and recurrent spontaneous abortion was downregulated." (PMID 37968664, 2023).
acute erythroleukemia (1 paper, 2022). "It has been more than 50 years since the THRA gene was cloned and characterized as a homolog of the v‐erbA gene, which is involved in neoplastic transformations leading to acute erythroleukemia and sarcomas, strongly suggesting its link with oncogenesis." (PMID 36217307, 2022). "Interestingly, the THRA gene was characterized in the early 1990s as the cellular homolog of the avian retroviral erytroblastoma virus v‐erbA, which is involved in neoplastic transformation leading to acute erythroleukemia and sarcomas, thus suggesting its link with malignancies." (PMID 36217307, 2022).
B cell deficiency (1 paper, 2023). A broad classification of disorders where circulating numbers of B lymphocytes are decreased or ineffective. "B‐cell lymphopoiesis was suppressed by the TRα1 mutation, and mutations in the THRA gene in patients could lead to B‐cell deficiency." (PMID 37773690, 2023).
bone tumors (1 paper, 2012). "High-level amplification of TGFβ2 (1q41), CCND3 (6p21), WI-6509 (11qtel), SHGC-5557 (12ptel), TCL1A (14q32.1), CREBBP (16q13.3), HIC1 (17p13.3), THRA (17q11.2), AFM217YD10 (17qtel), LAMA3 (18q11.2), RUNX1 (21q22.3) and D22S543 (22q11), was commonly observed in aggressive bone tumors." (PMID 23199169, 2012).
clear cell carcinomas (1 paper, 2020). "The general THRα has prognostic value only in clear cell carcinomas, where it is expressed at the highest immune scores." (PMID 32533406, 2020). "The expression of the general THRα is connected to significantly reduced overall survival in the subgroup of clear cell carcinomas." (PMID 32533406, 2020). "Among all subtypes of OvCa, clear cell carcinomas showed the highest THRα expression." (PMID 32533406, 2020).
colorectal adenocarcinoma (1 paper, 2022). The most common type of colorectal carcinoma. "Taken together, these data show that THRA promoter activity is positively regulated by the Wnt/β‐catenin pathway and CDX2 in human colorectal adenocarcinoma cell lines." (PMID 36217307, 2022).
colorectal tumors (1 paper, 2018). "Interestingly, in TCGA colorectal tumors, the levels of THRA expression were significantly and directly correlated with Wnt activity, once again reinforcing the link between TRα1 and the Wnt pathway." (PMID 30123421, 2018).
epilepsy (1 paper, 2023). A brain disorder characterized by episodes of abnormally increased neuronal discharge resulting in transient episodes of sensory or motor neurological dysfunction, or psychic dysfunction. "Patients who bear mutations in THRA are very likely to present significant neurological disorders such as epilepsy, motor incoordination or impaired cognitive function." (PMID 37854197, 2023).
glioblastoma (1 paper, 2014). The most malignant astrocytic tumor (WHO grade IV). "Interestingly, the thyroid hormone receptor (THRA) axis has also been shown to be essential for glioblastoma growth." (PMID 25026297, 2014).
invasive breast carcinoma (1 paper, 2021). A carcinoma that infiltrates the breast parenchyma. "The present study evaluates tumor-specific THRα-2 expression in invasive breast cancers and its association with tumor characteristics and long-term mortality in a large population." (PMID 34930399, 2021).
lung carcinoma (1 paper, 2021). "According to the protein atlas website, THRα was expressed in lung cancer cases with moderate intensity." (PMID 33846395, 2021).
lung fibrosis (1 paper, 2024). "Immunohistochemistry results showed that the expression of thyroid hormone receptors THRα and THRβ in the fibrotic areas of the lung increased in mice with lung fibrosis after BLM treatment." (PMID 39323641, 2024).
Miscarriage (1 paper, 2023). A pregnancy that ends at a stage in which the fetus is incapable of surviving on its own, defined as the spontaneous loss of a fetus before the 22th week of pregnancy. "Our results showed lower expression of TTR and THRα in placenta villi in miscarriage cases." (PMID 37968664, 2023). "Indeed, we found that villi angiogenesis was disrupted and the expression of THRα and VEGF was downregulated in miscarriage tissues." (PMID 37968664, 2023). "Accordingly, the protein abundance of THRα in villi was also significantly downregulated in the miscarriage group, but not the protein abundance of THRβ." (PMID 37968664, 2023). "The expression of THRα, but not THRβ, was significantly decreased in the placental villi of miscarriage patients." (PMID 37968664, 2023). "The protein abundances of TTR and THRα were downregulated in miscarriage group, but not THRβ." (PMID 37968664, 2023). "In miscarriage group, the gene expression of Dio2, Dio3, TTR and THRα, but not THRβ, MCT8 and OATP1A1, were downregulated." (PMID 37968664, 2023).
thyroid hormone resistance syndrome (1 paper, 2024). An inherited autosomal recessive trait, characterized by peripheral resistance to thyroid hormones and the resulting elevation in serum levels of thyroxine and triiodothyronine. "Molecules that modify THRA splicing may be developed into drugs for the treatment of thyroid hormone resistance syndromes." (PMID 39769274, 2024).
tumor (18 papers, 1989 to 2025). "Altogether, our results suggest a putative functional involvement of the transcriptional factors FOXJ3 and THRA in the 7SK-associated gene expression control and tumor migration in TSCC." (PMID 33868377, 2021). "We found strong associations between low THRα-2 tumor levels and several prognostically unfavorable tumor characteristics including ER negativity, high histological grade and larger tumor size." (PMID 34930399, 2021). "We found strong evidence of an association between low THRα-2 and unfavorable tumor characteristics, including estrogen receptor negativity: OR 4.04 (95% CI 2.28–7.15) and tumor size > 20–50 mm: OR 2.20 (95% CI 1.39–3.49)." (PMID 34930399, 2021). "The aim was to assess whether the expression of THRα-2 in breast tumors is associated with other tumor characteristics, as well as to evaluate any effect on survival." (PMID 34930399, 2021). "THRα-2 has previously been shown to be positively associated with ER; however in that study the authors found, in contrast to us, that THRα-2 was negatively correlated with tumor size and lymph node spread." (PMID 34930399, 2021). "The hypothesis leading up to the present study was that a lower expression of THRα-2 would be associated with prognostically unfavorable tumor characteristics and increased mortality." (PMID 34930399, 2021). "Our work describes, for the first time, the regulation of the THRA gene in specific cell and tumor contexts." (PMID 36217307, 2022). "The difference between the ER+ and ER- remained after adjusting for age at diagnosis, tumor size and ALNI, which indicates that the effect modification cannot be explained by the general association between THRα-2 and prognostically important characteristics." (PMID 34930399, 2021). "Logistic regression was used to calculate odds ratios (ORs) with 95% confidence intervals (CIs) for low vs high expression of THRα-2 related to specific tumor factors." (PMID 34930399, 2021). "A tissue micro array was constructed from stored tumor material and stained for THRα-2 using immunohistochemistry." (PMID 34930399, 2021). "Since our data demonstrate that selective THRA knockdown inhibited cell growth, a tumor promoting action of TRα is further affirmed." (PMID 26029931, 2015). "In addition, we have also identified a set of genes that are regulated in the opposite way by 7SK and FOXJ3/THRA, including four positive regulators in tumor migration (CXCL1, SYDE1, COL5A1, and HIF1A)." (PMID 33868377, 2021). "Compared with women with high THRα-2 tumor expression, women with low THRα-2 tumor expression were more likely to have ER- and PgR negative tumors, HER2-positive tumors, higher Ki67 and histological grade, as well as larger tumors, and were more likely to have ALNI." (PMID 34930399, 2021). "Women with low THRα-2 tumor expression were more likely to have tumors with other subtypes than Luminal A-like compared to women with high expression, for Luminal B-like: OR 1.99 (95% CI 1.34–2.97), HER2+: OR 2.42 (95% CI 1.38–4.27) and TNBC: OR 5.10 (95% CI 2.70–9.65)." (PMID 34930399, 2021). "It would be of great interest to demonstrate whether a directly functional link between FOXJ3/THRA and 7SK is involved in 7SK-mediated genes and 7SK-mediated tumor progression events in the near future." (PMID 33868377, 2021). "Recently THRA-rs939348 was confirmed as a risk factor for DTC, and one may speculate that its increased expression in ECR tumours is a persistent response to radiation DNA damage which may cooperate with other genes in DTC development." (PMID 26810418, 2016). "Favourable cases, we noted, are marked by THRA-mediated metabolic regulation, RXRG-driven tumour suppression, GCGR-maintained metabolic homeostasis, and FAAH-mediated resolution of inflammation." (PMID 41007296, 2025).
tumor (continued). "Reduced expression of eight immune‐related genes (IRGs) (NT5E, THRA, RBP1, TLR4, ITGA6, BMPR1B, ITGAV, SSTR1) in tumor strongly predicted better quality of prognosis, both in our patient cohort and in TCGA‐HNSC cohort." (PMID 37392167, 2023). "A relationship between tumor immune cells and angiogenesis in KIRC samples' data obtained from TCGA was studied, and RFX2, SOX13, and THRA were identified as the top three MTF in regulating angiogenesis signature in KIRC patients." (PMID 35096203, 2022). "Here, we identified 7SK acting as a novel tumor suppressor in TSCC, and suggested a putative functional involvement of FOXJ3 and THRA in 7SK-mediated TSCC progression." (PMID 33868377, 2021). "All in all, we have reported a tumor-suppressive role of 7SK in TSCC and suggested a putative functional involvement of FOXJ3 and THRA in 7SK-mediated TSCC progression." (PMID 33868377, 2021). "While the clinical significance of THRα has not been well defined, literature suggests that THRα1 is tumor-promoting while THRα2 has opposite effects on tumor growth and proliferation." (PMID 38785457, 2024). "The fact that knockdown of THRα1 and full length THRα failed to recapitulate the cytotoxic and anti-tumor effects of dronedarone suggests that the anticancer activity of this compound is not simply the consequence of antagonism of THRα1 or THRα." (PMID 30410118, 2018). "Notably, THRA and THRB mRNA expression were decreased, whereas expression of STMN1 was enhanced, in tumor specimens." (PMID 27934948, 2016). "Further analysis revealed THRα expression was not significantly deregulated across epithelial subtype (p = 0.116), tumour stage (p = 0.859) or menopausal status (p = 0.679, results not shown)." (PMID 25934412, 2015). "Interestingly, in patients with gastrointestinal tumors, it has been found that the expression of genes, such as TLRs, WFDC2, TTLL12, THRA, and EPHB3, which can trigger an immune response and release of pro-inflammatory factors and thus accelerate tumor cell invasion, is disturbed." (PMID 38243957, 2025).